CAV3 (caveolin 3)
Description:
May act as a scaffolding protein within caveolar membranes. Interacts directly with G protein alpha subunits and can functionally regulate their activity. May also regulate voltage-gated potassium channels. Plays a role in the sarcolemma repair mechanism of both skeletal muscle and cardiomyocytes that permits rapid resealing of membranes disrupted by mechanical stress (By similarity). Mediates the recruitment of CAVIN2 and CAVIN3 proteins to the caveolae.
Synonyms: VIP-21; LGMD1C; VIP21; LQT9; MPDT; RMD2
Tractability: Antibody: its Gene Ontology location is reachable by antibodies, with high confidence; UniProt places it where antibodies can reach, with medium confidence; the Human Protein Atlas places it where antibodies can reach. PROTAC: UniProt records ubiquitination sites on it.
Gene: Protein-coding gene on chromosome 3 (8,733,802 to 8,841,808, forward strand). Ensembl gene ENSG00000182533.
Subcellular location: Golgi apparatus membrane; Cell membrane; Membrane, caveola; Cell membrane, sarcolemma
Subcellular location (Human Protein Atlas): Plasma membrane; Vesicles
Pathways (Reactome):
Muscle contraction: Smooth Muscle Contraction
Gene Ontology:
Molecular function: calcium channel regulator activity; connexin binding; molecular adaptor activity; protein binding; protein-containing complex binding; sodium channel regulator activity; transmembrane transporter binding; potassium channel inhibitor activity; alpha-tubulin binding; enzyme binding; nitric-oxide synthase binding
Biological process: caveola assembly; negative regulation of calcium ion transport; negative regulation of cardiac muscle hypertrophy; negative regulation of cell size; negative regulation of MAPK cascade; negative regulation of sarcomere organization; regulation of calcium ion import; regulation of cardiac muscle cell action potential involved in regulation of contraction; regulation of cardiac muscle contraction; regulation of heart contraction; regulation of heart rate; regulation of membrane depolarization during cardiac muscle cell action potential; regulation of membrane potential; regulation of nerve growth factor receptor activity; regulation of signal transduction by receptor internalization; regulation of skeletal muscle contraction; regulation of sodium ion transmembrane transport; regulation of ventricular cardiac muscle cell membrane depolarization; regulation of ventricular cardiac muscle cell membrane repolarization; cell differentiation; cholesterol homeostasis; detection of muscle stretch; endocytosis; glucose homeostasis; intracellular protein localization; and 20 more
Cellular component: dystrophin-associated glycoprotein complex; endoplasmic reticulum; plasma membrane; sarcolemma; caveola; focal adhesion; membrane raft; neuromuscular junction; T-tubule; Z disc; cell surface; Golgi membrane; intercalated disc; membrane; protein-containing complex; vesicle
Genetic constraint (gnomAD): Loss-of-function variants: 7 observed, 12.36 expected, observed/expected ratio (o/e) 0.57, 90% interval 0.32 to 1.06. The upper end of that interval is the gene's LOEUF score, 1.06, which puts it in group 4 of 6, group 1 being the genes least tolerant of losing a copy. Missense variants: 144 observed, 180.5 expected, observed/expected ratio (o/e) 0.8, 90% interval 0.7 to 0.92. Synonymous variants: 85 observed, 76.45 expected, observed/expected ratio (o/e) 1.11, 90% interval 0.93 to 1.33.
Gene-disease validity (ClinGen):
ClinGen rates the evidence that CAV3 causes each of these diseases.
caveolinopathy (autosomal dominant): Definitive.
long QT syndrome (autosomal dominant): Limited.
Homologues: Orthologues: chimpanzee CAV3 (100% identical), macaque CAV3 (100% identical), rabbit CAV3 (98% identical), dog CAV3 (97% identical), guinea pig CAV3 (97% identical), pig CAV3 (97% identical), mouse Cav3 (95% identical), rat Cav3 (95% identical), zebrafish cav3 (74% identical), tropical clawed frog cav3 (67% identical), Caenorhabditis elegans cav-1 (26% identical), Caenorhabditis elegans cav-2 (25% identical). Paralogues in human: CAV1 (64% identical), CAV2 (34% identical).
Diseases named in the same sentence as CAV3 in open-access papers:
CAV3 is named in the same sentence as 116 diseases in open-access papers, as found by Europe PMC text mining. Sharing a sentence is not in itself a finding about the gene and the disease. The quoted sentences say what the papers report.
muscular dystrophies (32 papers, 2007 to 2025). "Mutations in CAV3 lead to caveolinopathies, which result in both muscular dystrophies and cardiac diseases." (PMID 38256054, 2024). "Other interesting features in both children were scoliosis and atlantoaxial dislocation, whereas we did not observe percussion-induced muscle mounding, a peculiar feature of CGL4 and of muscular dystrophy due to mutations in the CAV3 gene." (PMID 37501786, 2023). "In particular, changes in the expression of the caveolin-3 gene have been associated with different types of muscular dystrophies." (PMID 37327338, 2023). "Although the post-translational modifications of caveolin-3 have received limited attention, there is evidence to suggest that mutations in the CAV3 gene, which result in muscular dystrophy, are broken down through ubiquitination and proteasomal pathways." (PMID 38067108, 2023). "Mutations in CAV3 gene lead to a series of a family genetic disorders known as caveolinopathies, leading to rare forms of muscle dysfunction, such as muscular dystrophies, myopathies, and arrhythmias." (PMID 38067108, 2023). "These membrane repair proteins have been shown to contribute to human disease; disruption of the TRIM72/MG53, caveolin-3, and dysferlin complex, as well as mutations in the dysferlin and caveolin-3 genes, can result in muscular dystrophies." (PMID 35563723, 2022). "Together, results indicate that the overexpression of Cav-3 protein is involved in another causative process of chicken muscular dystrophy." (PMID 32825241, 2020). "Mutations in Caveolin-3 are known to cause muscular dystrophies that are collectively called caveolinopathies." (PMID 33228026, 2020). "Mutations in muscle-specific isoform Cav3 lead to muscular dystrophies characterized by muscle weakness, an increased number of centralized nuclei, and a high level of serum creatine kinase." (PMID 33228026, 2020). "One aspect that merits highlighting is that loss-of-function mutations within the muscle-specific caveolin isoform CAV3 or CAVIN1 causes muscular dystrophy." (PMID 30595521, 2019). "Mutations in the muscle-specific caveolin isoform Cav3 are associated with muscular dystrophy and other serious muscle abnormalities." (PMID 24052812, 2013). "The loss of caveolin-3 in the mouse reduces the number of caveolae in muscle and induces T-tubule abnormalities and a phenotype similar to muscular dystrophy." (PMID 23585895, 2013). "Mutations in the CAV3 gene cause caveolinopathies, which are types of muscular dystrophy." (PMID 36291131, 2022). "Interestingly, the signaling capacity of Cav3, in addition to its mechanoprotective role, is altered in myotubes expressing CAV3 mutations found in muscular dystrophy patients." (PMID 31862885, 2019). "We were appealed by the possibility to use of ISX for promoting caveolin and cavin expression as this could be of use for therapy of e.g. muscular dystrophy caused by CAV3 mutations, and therefore set out to determine its effect on these genes." (PMID 28542204, 2017). "Thus intramuscular p29 injection prevented myofiber hypotrophy in caveolin 3-deficient muscular dystrophy mice and induced postnatal myofiber hypertrophy in wild-type mice." (PMID 26226340, 2015). "Consequently, the loss of caveolin-3 in the mouse reduces the number of caveolae in muscle and induces T-tubule abnormalities and produces a phenotype similar to muscular dystrophy." (PMID 23585895, 2013). "However, loss of dysferlin staining is well recognised secondary phenomena in other limb girdle muscular dystrophies, most well characterised in mutations in caveolin-3 (LGMD 1C)." (PMID 23641709, 2013). "Thus, mutations in Cav-3 are linked to various muscular dystrophies." (PMID 40041164, 2025). "Pathways related to muscular dystrophy—primarily involving CAV3 and TTN—demonstrated moderate enrichment (p ≈ 10−4)." (PMID 41153379, 2025).
muscular dystrophies (continued). "The remaining six families had pathogenic variants in genes usually associated with muscular dystrophies (HNRNPDL, TOR1AIP1, SGCG, COL6A2, CAV3, TRIP4)." (PMID 38982518, 2024). "This review summarizes the major functions of Caveolin-3 in skeletal muscles and discusses its involvement in the pathology of muscular dystrophies." (PMID 33228026, 2020). "The exact functions of Cav3 in the pathology of various muscular dystrophies needs to be further investigated." (PMID 33228026, 2020). "Either the upregulation of caveolin-3 or the suppression of caveolin-3 via genetic ablation deteriorates muscular dystrophies such as DMD or limb-girdle muscular dystrophy-1C." (PMID 32244622, 2020). "Of note, the proteins encoded by genes linked to other muscular dystrophies such as COL6A1, CAV3, DYSF, DMD, TTN, and VCP and the strongest family sequencing candidates INTS1 and ANK2 were all found in nuclear envelope proteomics datasets." (PMID 31862442, 2020). "An increased level of Cav3 protein expression in skeletal muscle fibers of transgenic mice leads to muscular dystrophy, which in many features resembles DMD in humans." (PMID 33228026, 2020). "The third example relates to aberrations in three genes that separately cause different subtypes of muscular dystrophy: dystroglycan 1 (DAG1), dystrophin (DMD), and caveolin 3 (CAV3)." (PMID 24921629, 2014). "We injected a nanoparticle complex containing myostatin-siRNA and ATCOL (Mst-siRNA/ATCOL) into the masseter muscles of mutant caveolin-3 transgenic (mCAV-3Tg) mice, an animal model for muscular dystrophy." (PMID 23717655, 2013). "Caveolin 3 is involved in zebrafish muscle precursor differentiation, and Cav3 knockout mice exhibit a mild muscular dystrophy phenotype." (PMID 23663263, 2013). "Additionally, mutations of the muscle-specific proteins: Cav-3, dysferlin, and mitsugumin 53 (MG53) can disrupt the repair process, resulting in the progression of muscular dystrophies." (PMID 40041164, 2025). "An equivalent mutation in caveolin-3 (CAV3), P105L (curiously denoted as P104L in many studies), could show the phenotype of muscular dystrophies both in humans and/or animal models." (PMID 39201459, 2024). "Standard expression levels of CAV3 may be protective for the sarcolemma, while the upregulation of CAV3 may be detected in several muscular dystrophies owing to the probable compensation for additional functional deficiencies." (PMID 39201459, 2024). "The Hippo pathway is a potent regulator of muscle cells, and intriguingly, there are overlapping gene sets between those upregulated in muscular dystrophy, caused by CAVIN1 or CAV3 mutations, and those driven by deregulation of muscular YAP/TAZ-TEAD transcription." (PMID 30595521, 2019). "Mutations in CAV1, CAV3, and CAVIN1 lead to muscular dystrophies, lipodystrophy, and other phenotypes, which may be explained at least in part by such mechanoprotective role of caveolae." (PMID 31862885, 2019). "Furthermore, the significant role of Cav-3 in regulating NO within vascular disease extends to muscular dystrophy." (PMID 22934034, 2012). "An automated process has been developed for the detection of deletions, duplications/insertions and point mutations in any gene or family of genes and has been applied to ten genes known to bear mutations that cause muscular dystrophy: DMD; CAV3; CAPN3; FKRP; TRIM32; LMNA; SGCA; SGCB; SGCG; SGCD." (PMID 19835634, 2009). "Moreover, expression of caveolin 3, a specific muscular marker of caveolae that is altered in other forms of muscular dystrophies and is required for insulin-stimulated glucose uptake, was also normal in cardiac and skeletal muscles from dmpk−/− mice." (PMID 17987120, 2007). "Consistent implication of MYBPC3, CSRP3, CAV3, TCAP, and TTN across multiple pathways highlights convergent mechanisms, while moderate enrichment of muscular dystrophy pathways (involving CAV3 and TTN) further suggests overlapping pathophysiological networks." (PMID 41153379, 2025).
muscular dystrophies (continued). "A very similar phenotype has been observed in CAV3 knock out mice, which have no caveolae at the sarcolemma and exhibit a mild muscular dystrophy resembling RMD-2 in humans." (PMID 33228026, 2020). "Notably, while Cav-3 is also a key player in types of muscular dystrophy, which can have cardiovascular components, this pathological role of Cav-3 is outside of the scope of this review and will not be considered further." (PMID 22934034, 2012).
cardiac hypertrophy (27 papers, 2009 to 2025). "Specifically, previous studies have shown that the loss of caveolin-3 causes cardiac hypertrophy via hyperactivation of p42/44 MAPK cascade and the dysregulation of muscle calcium homeostasis." (PMID 41144497, 2025). "Several mutations in Cav3, such as Thr63Ser, Thr78Met, Ala46Thr, and the deletion of Phe96, are known to cause cardiac hypertrophy in human patients." (PMID 33228026, 2020). "The present data show that TAC caused qualitatively similar changes in Cav‐3 OE mice to those reported previously in WT mice: cardiac hypertrophy and failure, with disrupted cell structure and function." (PMID 30786093, 2019). "Loss-of-function mutations and knockout of Cav-3 are also associated with cardiac hypertrophy, consistent with a role for loss of Cav-3 expression in age-related hypertrophic signaling." (PMID 29236992, 2018). "Previous work has shown that transverse aortic constriction (TAC)-induced hypertrophy and HF are associated with decreased cardiac Cav-3 expression." (PMID 30028203, 2018). "PTRF/Cavin-1 deficiency shows reductions of caveolae and caveolin-3 (Cav3) protein expression in skeletal muscle, and Cav3 deficiency in the heart causes cardiac hypertrophy with loss of caveolae." (PMID 27612189, 2016). "Cav-3 also is involved in the protein kinase A-dependent stimulation of T-type Ca2+ channels, which are re-expressed in the adult heart during hypertrophy and associated with cardiac dysfunction in heart failure." (PMID 23060817, 2012). "Loss of Cav-3 has resulted in significant cardiac hypertrophy and reduced myocardial function." (PMID 40041164, 2025). "Further inspection of the top differentially expressed genes for LR and LRI showed a strong downregulation of Caveolin-3 (CAV3) that has been implicated in the biogenesis of t-tubules and moreover been shown to be associated with cardiac hypertrophy and heart failure when expression is decreased." (PMID 35686037, 2022). "Moreover, mutations in Cav3 have been detected in various cardiovascular diseases such as arrhythmias, cardiac hypertrophy, and injury after myocardial ischemia/reperfusion." (PMID 33228026, 2020). "A high embryonic level of Cav3 channel expression is associated with expanded roles in the early proliferative states such as myoblast fusion, and recapitulated to high levels in disease states such as cancer and ventricular hypertrophy." (PMID 22719839, 2012). "Caveolin-3 exerts its effects as a scaffolding and regulatory protein for signaling molecules and moderators of ion channels and has already been linked to numerous human disease states, such as long QT syndrome, sudden infant death syndrome, myocardial hypertrophy, and diabetic cardiomyopathy." (PMID 35329921, 2022). "Because PKCα contributes to cardiac hypertrophy and LV dysfunction in pressure overload, while loss of caveolin 3 promotes cardiomyopathy, the altered expression and distribution of these proteins may help explain the increased pathological hypertrophy observed in MACF1 KO mice after TAC." (PMID 24086300, 2013). "Additionally, natriuretic peptides that can modulate cardiac hypertrophy by regulating the adaptive response of the heart to hemodynamic overload via diuretic, natriuretic and vasodilatory action, are associated with caveolae and Cav-3." (PMID 23060817, 2012). "There are three caveolin isoforms, and previous research has shown Cav3 knockout mice show signs of muscle myopathic changes, cardiac hypertrophy, and cardiomyopathy." (PMID 33679876, 2021). "It is surprising to see reduced CAV3 expressions in pathological cardiac conditions, such as myocardial infarction, heart failure, and hypertrophy." (PMID 33927797, 2021). "The Cav3 KO mice show signs of cardiac hypertrophy and reduced function of the heart as characterized by ventricular dilation and reduced contractility." (PMID 33228026, 2020).